PTGER3 (prostaglandin E receptor 3)
Diseases named in the same sentence as PTGER3 in open-access papers (continued):
Sharing a sentence is not in itself a finding about the gene and the disease.
leiomyoma (1 paper, 2023). A well-circumscribed benign smooth muscle neoplasm characterized by the presence of spindle cells with cigar-shaped nuclei, interlacing fascicles, and a whorled pattern. "Secondly, PTGER3 was highly expressed on the smooth muscle cells in pseudocapsule compared to leiomyoma." (PMID 37215998, 2023). "Besides AVPR1A and OXTR, we further found PTGER3, one of top DEGs, was highly expressed on the smooth muscle cells in pseudocapsule compared to leiomyoma, indicated that PGE2 might be another candidate." (PMID 37215998, 2023).
periodontal disease (1 paper, 2019). "PTGER3 (rs74086974; p-value 3.18 × 10− 6) is a candidate gene for the outcome of periodontal disease therapy, and MIR186 (rs74086974) is differentially expressed between gingiva in health versus periodontitis." (PMID 31533690, 2019).
prediabetes (1 paper, 2022). "Expression of Ptger3 (the gene encoding EP3) in the islet is dynamically regulated in pathophysiological conditions such as prediabetes, T1D, and/or T2D." (PMID 35448529, 2022).
pulmonary fibrosis (1 paper, 2022). Chronic progressive interstitial lung disorder characterized by the replacement of the lung tissue by connective tissue, leading to progressive dyspnea, respiratory failure, or right heart failure. "By analyzing the target interaction network VCAM1,RELA,CDK2,JUN,CDK1,HSP90AA1,NOS2, SOD1,CASP3,AHSA1, PTGER3 are at the core of the network, which can be regarded as the key targets of Astragalus polysaccharides in treating pulmonary fibrosis." (PMID 35370663, 2022).
renal cell carcinoma (1 paper, 2021). "In renal cell carcinoma (RCC), the lower expression of PTGER3 was correlated with a worse prognosis." (PMID 33435900, 2021).
skin aging (1 paper, 2023). The gradual irreversible changes in structure of skin that occur as a result of the passage of time.. "Then, we confirmed the down-regulated expressions of ABCC4, PTGER3, BCEH, HPGD, and MOXD1 in normal group, while AR, CXCR2, HSD17B2, ODC1, PI3, PLAU and THBS2 were up-regulated in skin aging group." (PMID 37310405, 2023).
Streptococcus pneumoniae infection (1 paper, 2018). "Therefore, increased AM expression of PTGER3 following EC use may increase the susceptibility of EC users to Streptococcus pneumoniae infection." (PMID 29754582, 2018). "Deletion of PTGER3 was shown to improve pulmonary host defense and protect mice from death following Streptococcus pneumoniae infection, and other studies suggest that prostaglandins may play key roles in pulmonary host defense." (PMID 29754582, 2018).
Ureteral obstruction (1 paper, 2012). Obstruction of the flow of urine through the ureter. "Prostaglandins play an important role in ureteral obstruction, but the detailed expression profiles of the prostaglandin receptors (PTGER1, PTGER2, PTGER3, PTGER4, PTGFR) remain unknown in the different parts of the human ureter." (PMID 23227994, 2012).
tumor (57 papers, 2005 to 2026). "The PGE2, PGI2, and LTB4 pathways have been linked with clinical progression through the PGE2 receptor PTGER3 on tumor cells, expression of the PGI2-synthesizing enzyme PTGIS by tumor cells and TAMs, as well as release of LTB4 into the TME by both cell types." (PMID 28275576, 2017). "A major target of their products seem to be TAMs, which express considerable higher levels of the PGE2 and PGI2 receptor genes PTGER2, PTGER4, and PTGIR with the exception of PTGER3 expressed only by a small subset of tumor cells." (PMID 27215396, 2016). "Both receptors appear to have similar roles in stromal regulation, but show different behaviors in the tumor: PTGER3 is the only receptor whose overexpression is maintained in the tumor tissue." (PMID 26207152, 2015). "Most of the transcriptomic signatures (without subgroup analysis) still show acceptable tumor specificity with the exception of the signature containing PTGDS, CBR3, PTGIR, PTGFR, PTGDR2, and PTGER3 genes in HNSC tumor, which is similar to other tumors (BRCA, CESC, LUAD, SARC, and UCES)." (PMID 35453789, 2022). "PTGER3 (EP3) has been shown to be involved in the activation of Src signaling via Prostaglandin E2 (PGE2), and host stromal PGE2-EP3 signaling appears critical for tumor-associated angiogenesis and tumor growth." (PMID 17663764, 2007). "Interesting, it appears that PTGER3 expression is non-significant at mRNA level, while the protein expression appears significant in the tumor sections, which may be caused by the regulation of epigenetics." (PMID 34966691, 2021). "In non-tumor cells (HaCaT), the effect was inverse, with an upregulation of PTGS2 and its receptors (PTGER2, PTGER3, and PTGR4), indicating the pro-inflammatory effect of piperine on non-tumor cells." (PMID 36678600, 2023). "The receptors PTGER2, PTGER3, and PTGER4 exhibited reduced gene expression in all tumor cells, indicating a reduction in the action of PGE2 on these receptors." (PMID 36678600, 2023). "The comparatively lower expression of AGXT, PTGER3 and SLC12A3 in tumours correlates with worse prognosis in KIRC patients, while higher expression of ALOX5 predicts reduced survival." (PMID 32144299, 2020). "Consistently, we found that ALOX5 was upregulated in the tumour samples, while AGXT, PTGER3, and SLC12A3 were downregulated in the tumour samples." (PMID 32144299, 2020). "We identified three genes (AGXT, PTGER3 and SLC12A3) with lower mRNA levels in tumour samples, and patients with a high expression of these three genes exhibited prolonged survival." (PMID 32144299, 2020). "This analysis identified three genes expressed in tumor cells, i.e. ALOX15B, the leukotriene B4 receptor gene LTB4R2 and the PGE2 receptor gene PTGER3." (PMID 27215396, 2016). "The opposite trend was observed with PTGER4, PTGDS, PTGER3, PTGIS, PTGFR, and PTGS1 genes, which showed overexpression in the adjacent non-tumor tissue, followed by downregulation in the tumor." (PMID 26207152, 2015). "Seven of the twelve differential genes found amongst individual tumor ANOVA analyses were common to the linear discriminant gene profile (LD-p54): ANGPLT4, COL1A1, GP2, GPR57, LAMB3, PCDHB9, and PTGER3." (PMID 15836779, 2005). "On the one hand, ADRB2 (SMD = −1.46; 95% CI −2.02, − 0.91; P < 0.01), PDE1C (SMD = −0.75; 95% CI – 1.11, −0.39; P < 0.01) and PTGER3 (SMD = −0.58; 95% CI −1.08; −0.07; P < 0.01) were down-regulate in the cancer groups, which might be a tumor suppressor gene." (PMID 34646828, 2021). "For instance, using WGCNA and a protein-protein interaction network, a recent study analyzed the gene expression pattern of 26 pairs of tumor tissues/adjacent tissues and identified four hub genes involved in the progression of KIRC, including AGXT, PTGER3, SLC12A3, and ALOX5." (PMID 33110456, 2020).
tumor (continued). "Thus, estrogen may promote cell survival and tumor growth by increasing expression of the anti-apoptotic PCP4 gene and by suppressing the expression of growth inhibitory receptors PTGER3 and TGF-β R2." (PMID 17407572, 2007). "The expression of the negative genes (ELOVL5, PTGER3, KIAA1324, and CYBRD1) in tumors was lower than that in normal and tumor-adjacent tissues." (PMID 36341435, 2022).
cancer (37 papers, 2006 to 2025). A tumor composed of atypical neoplastic, often pleomorphic cells that invade other tissues. "A very strong adverse effect on RFS (p = 0.0001) was seen with TGFB3, in line with the central role of the associated signaling pathways in cancer, and with PTGER3 (p <0.0001), encoding a prostaglandin E2 receptor." (PMID 27215396, 2016). "The results showed that high expression of TSLP, RASGRP1, APOD, and PTGER3 was correlated with cancer cell drug sensitivity to a variety of chemotherapeutic drugs, especially APOD, which was highly correlated with drug sensitivity to ARQ-680, SB-590885, PLX-4720, vemurafenib, and others." (PMID 36467500, 2022). "CYSLTR1 and PTGER4 are primarily expressed by immune cells in human cancers, while LTB4R, PTGER1 and PTGER3 are found in neuroendocrine and tuft cells." (PMID 37386128, 2023). "Experiments using ROS and nitrogen oxide synthase (NOS) inhibitors demonstrated the ROS- and reactive nitrogen species (RNS)-independent regulation of PTGER3 and HSPA6 when U937 cancer cells were treated with CAP." (PMID 32947888, 2020). "Among the module genes, BUB1, GATM, PLCE1, NEGR1, PTGER3 and SH3RF2 were differentially expressed in three or more cancer tissues." (PMID 28694494, 2017). "This revealed up to 12 genes that are suppressed in CRC, including genes that had been previously found misregulated in cancer, such as HPGD, PTGIS, PTGER3, and AKR1B1." (PMID 26207152, 2015). "Receptors for eicosanoids in PRN and PRT cancer models are primarily located in immune cells and fibroblasts: Fpr2 is located in granulocytes, Cysltr1 and Ptger4 in macrophages (and B cells in PRT), Ptger3 in fibroblasts, while Ptgir is found in smooth muscle cells." (PMID 37386128, 2023). "In addition to the C3, for these genes (CXCL8, CX3CR1, GRM8, HTR1B, HTR1D, PTGER3, SSTR1 and SUCNR1) were related to survival in the ACC and it was also could be useful in other cancers 24-31." (PMID 34220331, 2021). "Moreover, each physicochemical component of CAP regulated a unique set of genes wherein the non-ROS constituents of CAP targeted HSPA6 and PTGER3, which showed anti-proliferative and pro-apoptotic activity in the cancer cells." (PMID 32947888, 2020). "PTGDR, PTGDR2, PTGER1, PTGER3, and PTGFR genes have the median expression value of about 1 FPKM (Fragments Per Kilobase Million), while other genes are expressed in the range of 1–5 FPKM, regardless of cancer specificity." (PMID 35453789, 2022).
infection (10 papers, 2011 to 2025). The state of being infected such as from the introduction of a foreign agent such as serum, vaccine, antigenic substance or organism. "Since the effector function of PGE2 produced by myeloid cells depends on its binding to EP receptors, we studied gene expression of its 4 receptors, EP-1 (Ptger1), EP-2 (Ptger2), EP-3 (Ptger3) and EP-4 (Ptger4), in hearts of mice during infection." (PMID 26305786, 2015). "Potential candidate genes in this locus are Ptgfr (prostaglandin F receptor) [MGI:97796] and Ptger3 (prostaglandin E receptor 3 (subtype EP3)) [MGI:97795], as prostaglandins play a suppressive role in infection with African trypanosomes." (PMID 21666791, 2011).
colon (2 papers, 2007 to 2015). "Indeed, not only colorectal, but also liver, stomach, and pancreas tumors present high rates of hypermethylation of PTGIS, AKR1B1, PTGER3, and PTGFR." (PMID 26207152, 2015).
brain diseases (1 paper, 2022). "Altered PTGER3 expression in the microglia leads to acute or chronic microglial activation in brain diseases like AD." (PMID 34981809, 2022).
PTGER3 also shares sentences with these, for which no sentence is quoted: Stroke (7 papers); cardiovascular disease (4); Insulin resistance (4); liver fibrosis (4); colorectal cancer (3); heart failure (3); Hyperglycemia (3); ischemic stroke (3); Lewis lung carcinoma (3); squamous cell carcinoma (3); adenocarcinoma (2); allergic conjunctivitis (2); Allergy (2); atherosclerosis (2); cervical dysplasia (2); colitis (2); COVID-19 (2); diabetic kidney disease (2); glioma (2); gynecological cancer (2); injury (2); Intestinal tumors (2); intracerebral hemorrhage (2); lung carcinoma (2); nasal polyp (2); pancreas cancer (2); skin cancers (2); type 2 diabetes (2); adenoma (1); allergic contact dermatitis (1).
A further 71 diseases each share a sentence with PTGER3 in 1 paper.